CTSD (cathepsin D)
Diseases named in the same sentence as CTSD in open-access papers (continued):
Sharing a sentence is not in itself a finding about the gene and the disease.
tonsillitis (1 paper, 2025). Inflammation of the tonsillar tissue. "In this pathway, the Cathepsin D level was increased in CD19+ cells of patients with OSAS compared to those of patients with tonsillitis." (PMID 40724870, 2025).
ulcerative colitis (1 paper, 2024). An inflammatory bowel disease involving the mucosal surface of the large intestine and rectum. "Additionally, in ulcerative colitis, zyxin (ZYX), RhoB, and cathepsin D (CTSD) have been identified as core genes through single-cell RNA sequencing (scRNA-seq) analysis." (PMID 38712343, 2024).
urothelial bladder cancer (1 paper, 2016). "CTSD and CTSB activities in the sera of patients with urothelial bladder cancer were identified to be directly proportional to disease severity, and were significantly higher compared to those of the control group." (PMID 26995190, 2016).
viral infections (1 paper, 2014). "Most overexpressed proteins are involved in immune response, as T-cells activation and functions (CD59, IL12A) or the response to bacterial and viral infections (CTSD, TRIM22)." (PMID 25594007, 2014). "However, some of these proteins also are involved in immune response and inflammation, as T-cells function and activation (CD59, IL12A); others are involved in the response to bacterial and viral infections (CTSD, TRIM22)." (PMID 25594007, 2014).
tumor (181 papers, 1991 to 2026). "Loss of CTSD in tumor cells mimicked the effect of endothelial PEAR1 expression in vitro and in vivo." (PMID 41185039, 2025). "CTSD, a lysosomal protease, is involved in extracellular matrix degradation and tumor invasion, and its overexpression has been associated with increased aggressiveness in multiple cancer types." (PMID 40496864, 2025). "Our data identify a mechanism underlying tumor cell dormancy and suggest CTSD and LOXL2 as targets for approaches to promote dormancy." (PMID 41185039, 2025). "Tumours positive for both ER and PgR were also associated with positive Cathepsin D expression (p = 0.037)." (PMID 38578521, 2024). "Tumours positive for Cathepsin D were associated with ER-positive (p = 0.006) and HER2-negative (p = 0.006) status." (PMID 38578521, 2024). "This was consistent with another study which also found a significant association of Cathepsin D expression with tumour grade (p < 0.001)." (PMID 38578521, 2024). "Statistical analysis demonstrated a highly significant association of Cathepsin D with poor prognostic variables including high tumour grade (p < 0.007) and poor NPI (p = 0.002)." (PMID 38578521, 2024). "Cathepsin D expression was also associated with highly increased risk of subsequent metastasis, recurrence and tumour grade." (PMID 38578521, 2024). "Positive Cathepsin D expression was associated with high-grade tumours (p = 0.007), high pleomorphism score (p = 0.002), poor NPI score (p = 0.002), development of distant metastasis (p < 0.0001) and recurrence (p = 0.005)." (PMID 38578521, 2024). "The defective intracellular sorting and the escape from lysosomal targeting led to aberrant secretion of cathepsin D precursor, an event associated with increased tumor size, grading and chemoresistance in a variety of malignancies." (PMID 35563171, 2022). "Different families of proteases, including MMPs, cathepsin D, and urokinase plasminogen activator, have been implicated in tumor cell invasion." (PMID 34452576, 2021). "CTSD overexpression is reported to be associated with higher recurrence rates and shorter disease-free and overall survival in various tumor cells." (PMID 34062746, 2021). "Together, these studies reveal a tumor cell-autonomous effect of CTSD deficiency, and establish a pivotal role of this protease in the cellular response to oncogenic stimuli." (PMID 33046706, 2020). "Regarding underlying mechanisms of pro-cathepsin D, previous studies suggested that they are involved in multiple stages of tumour progression including proliferation, invasion, metastasis, angiogenesis, and apoptosis." (PMID 32867726, 2020). "In PyMT cells, CTSD deficiency stalled tumor cell proliferation under short-term starvation by preventing the recruitment of mTORC1 and its activation at the lysosomal membrane resulting in enhanced autophagic flux and cellular quiescence." (PMID 33046706, 2020). "In line, CTSD-deficient tumors started to grow with a two-month delay and quiescent Ctsd-/- tumor cells re-started proliferation upon long-term culture." (PMID 33046706, 2020). "CTSD is an aspartic endoprotease overexpressed and secreted by several tumor cell types, known to be associated with tumor aggressiveness and to be involved in PCa development promoting malignancy of prostatic epithelium." (PMID 32421745, 2020). "This was based upon subgroups containing subglottic- or transglottic- tumors, where patients with tumor-positive lymph nodes showed positive for cathepsin D expression and were classed as being at a higher risk for relapse." (PMID 33266503, 2020). "In summary, CTSD deficiency renders tumor cells quiescent, increases their lysosomal compartment under FCS starvation, and rewires the lysosomal proteolytic system." (PMID 33046706, 2020). "Rather we found that CTSD-deficient tumor cells that escaped quiescence changed from an epithelial to a mesenchymal-like morphology, suggesting EMT." (PMID 33046706, 2020).
tumor (continued). "CTSD-deficient tumor cells were able to adapt to long-term FCS starvation as indicated by resumed proliferation." (PMID 33046706, 2020). "We provide evidence for a tumor cell-specific effect of CTSD deficiency on tumor development in PyMT mice." (PMID 33046706, 2020). "On average, the proportion of CTSD-deficient cells decreased to 52% in the outgrown tumors, while CTSD-competent cells rose from 12 to 48% of the tumor masses." (PMID 33046706, 2020). "To further study the escape of the transient growth block caused by CTSD deficiency, we extended the cultivation time of tumor cells in 1% FCS starvation medium from < 2 weeks to ≥ 8 weeks, a condition we defined as 1% FCS long-term (1% FCS LT)." (PMID 33046706, 2020). "Based on its activating phosphorylation and transcriptional induction of its target genes, we think that CREB is important for CTSD-deficient tumor cells to overcome the proliferation block during starvation." (PMID 33046706, 2020). "One downstream target of these kinases specifically activated by phosphorylation in CTSD-deficient previously quiescent tumor cells was CREB." (PMID 33046706, 2020). "have demonstrated increased cathepsin D expression in cells from the main tumor body in late stage CRC to be significantly associated with subsequent distant metastasis and reduced cancer-specific survival." (PMID 30177970, 2018). "A number of clinical studies have been performed to evaluate the diagnostic and prognostic significance of elevated CTSB and CTSD concentrations in tumor cytosols." (PMID 26995190, 2016). "Among the patients with positive lymph nodes, those with tumor cells immunopositive for CTSD had a higher risk of relapse." (PMID 26995190, 2016). "CTSB and CTSD contribute to tumor cell invasion and angiogenesis and are commonly associated with metastasis." (PMID 24717913, 2014). "Many tumors have altered processing, secretion, and activity levels of CTSD, and they are often associated with aggressive behavior, stimulating tumor cell proliferation, invasion, and metastases." (PMID 22084687, 2011). "An increased level of cathepsin-D in tumour extracts has been found to be associated with a poor relapse-free and overall survival." (PMID 9888472, 1999). "There is a strong positive association between expression of cathepsin-D and the presence of tumour in axillary lymph nodes (P < 0.006)." (PMID 8471433, 1993). "In addition, several biomarkers are associated with tumor-promoting signaling pathways and adverse clinical outcomes; for instance, cathepsin D, miR-421, and HMGB1 are frequently overexpressed in osteosarcoma and linked to enhanced tumor progression." (PMID 40864783, 2025). "Cathepsin D knock-down in zebrafish was also associated with skin hyperpigmentation, that might suggests cathepsin D involvement in pigmentation changes during hypoxia exposure of cancer cell lines." (PMID 36776379, 2022). "Indeed, phosphorylation of a major mTORC1 target, namely the P70S6K, was reduced indicating impaired mTORC1 activity in CTSD-deficient tumor cells." (PMID 33046706, 2020). "In addition, several proteins such as enolase, vimentin, peroxiredoxin 5, Hsp 70, periostin precursor, RhoA, cathepsin D preproprotein, and annexin 1 were found to be associated with the tumor responses to treatment within each subtype." (PMID 22110952, 2011). "Consistently, tumor cells showed constitutive Cathepsin D maturation and enhanced sensitivity to NFU-induced lysosomal perturbation." (PMID 42120505, 2026).
tumor (continued). "In physiological conditions, pro-CTSD is found in the intracellular space, while it has been shown that, in pathological conditions, the pro-CTSD/CTSD levels ratio correlates with tumor aggressiveness and prognosis." (PMID 41227296, 2025). "Tumor cells with suppressed CTSD expression showed increased dormancy and decreased metastatic potential in vivo." (PMID 41185039, 2025). "Our data show that the induction of tumor cell dormancy by endothelial PEAR1 also involves the sequestration of CTSD." (PMID 41185039, 2025). "We constructed xenograft tumor models and liver metastasis models in nude mice by injecting CTSD WT and CTSD N263Q SW480 cells." (PMID 39716927, 2025). "To investigate the role of CTSD in cancer, we first examined the protein expression of CTSD in various cancer types using the Clinical Proteomic Tumor Analysis Consortium (CPTAC) database." (PMID 40796615, 2025). "Like TIMP1 and ICAM1, CTSD is typically overexpressed in PDAC and has been implicated in cancer cell proliferation, migration, and tumor invasion." (PMID 40507347, 2025). "Since LOXL2 is well known to inhibit tumor cell dormancy and to promote metastasis and tumor growth, we focused our anlaysis on the function of CTSD." (PMID 41185039, 2025). "Currently, CTSD has attracted significant attention in cancer research due to its overexpression in various cancers, where it promotes tumor cell proliferation, invasion, and metastasis." (PMID 40969353, 2025). "This led us to propose a model in which PEAR1 promotes tumor cell dormancy by extracellular binding of CTSD and LOXL2, thereby preventing CTSD and LOXL2 to exert pro-proliferative activity." (PMID 41185039, 2025). "This is consistent with previous studies showing that CTSD increased tumor cell proliferation and prevented tumor cells from entering a quiescent state." (PMID 41185039, 2025). "In ER-positive tumours, patients with positive Cathepsin D expression showed significantly shorter BCSS than those negative for the marker (p = 0.01)." (PMID 38578521, 2024). "In ER-positive tumours, patients with positive Cathepsin D expression showed significantly shorter disease-free interval (p = 0.005 for recurrence and p < 0.0001 for metastasis) than those negative for the marker." (PMID 38578521, 2024). "Our group previously explored the role of CTSD in skin photoaging and found that CTSD was negatively correlated with AGEs accumulation." (PMID 39871835, 2024). "ER-positive tumours expressing Cathepsin D and treated with tamoxifen demonstrated a significantly higher risk of distant metastasis." (PMID 38578521, 2024). "Cathepsin D induces cell proliferation, metastasis, tumour invasion, angiogenesis and apoptosis in cancer and stromal cells." (PMID 38578521, 2024). "Although cathepsin D (Cat D) has been reported as a procarcinogenic factor, little is known about the functional role of Cat D in the tumor microenvironment (TME)." (PMID 38297161, 2024). "Using a mouse xenograft tumor model, the authors demonstrated that the application of human anti-cathepsin D antibodies inhibited tumor growth by preventing macrophage recruitment and triggered natural killer cell activation." (PMID 37896224, 2023). "In conclusion, our newly developed targeting system based on liposome-bound pepstatin A successfully inhibited cathepsin D and demonstrated efficient binding to the tumor cell surface." (PMID 37896224, 2023). "Cathepsin D (CatD) is a lysosomal protease which hydrolyses proteins during autophagy aimed at tumor cell survival under stress conditions." (PMID 36768815, 2023). "The successful targeting of cathepsin D was confirmed using recombinant cathepsin D and in tumor cell lines, showing the feasibility of this targeting approach and its potential for in vivo use in theragnostic applications." (PMID 37896224, 2023).
tumor (continued). "The proteolytic activity of cathepsin D leads to pro-tumor factor activation and extracellular matrix cleavage." (PMID 37896224, 2023). "In the MDA-MB-231 metastatic xenograft model, the anti-cathepsin D antibody prevents M2-like macrophages and the recruitment of myeloid-derived suppressor cells, leading to less immunosuppression in the tumor microenvironment." (PMID 35186475, 2022). "This agrees with our results indicating the upregulation in the tumor margin of both CTSD and NAPA, which are present in the phagosome maturation pathway." (PMID 35512017, 2022). "Following KLK6 inhibition, KLK6 mRNA expression; metabolic activity, indicative of cell viability; and secretion of KLK6 were reduced in our tumour spheroids, while the secretion of cathepsin D and uPA was increased." (PMID 34439122, 2021). "CTSD is active in low pH environments, stimulating tumor cells for pro-invasive and pro-metastatic capacities." (PMID 33861751, 2021). "The co-localization of cathepsin B and cathepsin D has been previously demonstrated in cSCC, with cooperation between the two enzymes suggested to play a role in tumor invasion and metastasis." (PMID 34621666, 2021). "These proteases, including MMP-3, MT1-MMP (MMP-14), cathepsin B and cathepsin D, have been reported to play important roles in cancer invasion, in vivo tumor growth and distant metastasis." (PMID 33110168, 2020). "CTSD was detected in more invasive areas of the tumor in both epithelial cells and the adjacent stromal compartment, but not in normal mucosa, supporting a role for CTSD in L1-mediated CRC progression." (PMID 33228199, 2020). "For instance, cathepsin D is a catalytic protein that stimulates cancer cell proliferation and tumor angiogenesis and can also provide protection against tumor apoptosis." (PMID 32984024, 2020). "Based on our results, we would rather agree with studies assigning CTSD in tumor cells prognostic significance." (PMID 33046706, 2020). "This cancer cell-specific secretion of pro-CTSD can be targeted by antibodies to elicit an anti-tumor immune response." (PMID 33046706, 2020). "In particular, high levels of CTSD were found in the invasive front of CRC tumor tissues, thereby suggesting CTSD as a promising biomarker for CRC progression." (PMID 32878319, 2020). "Over the last three decades, extracellular cathepsin D has been reported to play a pro-tumourigenic role, inducing tumour growth, invasion and angiogenesis." (PMID 32645977, 2020). "In order to study the role of CTSD in PyMT cancer cells, we generated a tumor cell line from a Ctsdfl/fl;mTmG mouse and introduced a doxycycline (Dox)-inducible cre recombinase expression system." (PMID 33046706, 2020). "As a result, research on CTSD in tumor biology is lagging far behind that on cysteine-type cathepsins." (PMID 33046706, 2020). "Here, 43 low malignant potential and 80 invasive tumor samples were analysed with 65.1% and 43.7% showing positive for cathepsin D expression, respectively." (PMID 33266503, 2020). "Half of the mice with a CTSD deletion in mammary epithelial cells reached an end-stage tumor burden at 28 weeks in contrast to LysM-cre;Ctsd−/− (20 weeks) and control (22 weeks) mice." (PMID 33046706, 2020). "Apart from its enzymatic role inside the lysosomes and in the tumor cell microenvironment (the secreted form of cathepsin D), it is also well known to be involved in the regulation of cell death." (PMID 31248089, 2019). "Research into the role of cathepsin B and cathepsin D in tumorigenesis, so far, has mainly focused on their independent influence on tumor invasiveness." (PMID 30949483, 2019). "The mechanism/s by which CTSD promotes tumorigenesis are still unclear and suggest both mitogenic, paracrine effects on stromal cells in the tumor environment and an interaction with a yet to be detected cell surface membrane receptor in the carcinoma cells." (PMID 31497251, 2019).